NTM (neurotrimin)
Description:
Neural cell adhesion molecule.
Synonyms: hNT; IGLON2; NTRI; CEPU-1
Tractability: Antibody: its Gene Ontology location is reachable by antibodies, with high confidence; UniProt places it where antibodies can reach, with medium confidence; UniProt predicts a signal peptide or a membrane-spanning region. PROTAC: its protein half-life has been measured.
Gene: Protein-coding gene on chromosome 11 (131,370,478 to 132,336,822, forward strand). Ensembl gene ENSG00000182667.
Subcellular location: Cell membrane
Pathways (Reactome):
Metabolism of proteins: Post-translational modification: synthesis of GPI-anchored proteins
Gene Ontology:
Molecular function: protein binding
Biological process: cell adhesion; heterophilic cell-cell adhesion; neuron recognition; regulation of synapse assembly
Cellular component: extracellular region; plasma membrane; postsynaptic density membrane; presynaptic active zone membrane
Genetic constraint (gnomAD): Loss-of-function variants: 13 observed, 42.04 expected, observed/expected ratio (o/e) 0.31, 90% interval 0.2 to 0.49. The upper end of that interval is the gene's LOEUF score, 0.49, which puts it in group 2 of 6, group 1 being the genes least tolerant of losing a copy. Missense variants: 359 observed, 451.06 expected, observed/expected ratio (o/e) 0.8, 90% interval 0.73 to 0.87. Synonymous variants: 180 observed, 182.51 expected, observed/expected ratio (o/e) 0.99, 90% interval 0.87 to 1.12.
Homologues: Orthologues: macaque NTM (99% identical), rat Ntm (98% identical), guinea pig NTM (95% identical), chimpanzee NTM (93% identical), mouse Ntm (88% identical), rabbit NTM (84% identical), pig NTM (82% identical), dog NTM (82% identical), tropical clawed frog ntm (70% identical), zebrafish opcml (54% identical), Drosophila melanogaster DIP-kappa (30% identical), Drosophila melanogaster DIP-zeta (29% identical), and 11 more. Paralogues in human: OPCML (68% identical), LSAMP (49% identical), NEGR1 (46% identical), IGLON5 (45% identical), IGSF5 (16% identical).
Diseases named in the same sentence as NTM in open-access papers:
NTM is named in the same sentence as 31 diseases in open-access papers, as found by Europe PMC text mining. Sharing a sentence is not in itself a finding about the gene and the disease. The quoted sentences say what the papers report.
melanoma (2 papers, 2020 to 2022). A malignant, usually aggressive tumor composed of atypical, neoplastic melanocytes. "The most relevant finding has been the association with NTM (neurotrimin) gene, recently related not only to neural cell development and survival but also to skin cell adhesion and increased risk of melanoma." (PMID 32070410, 2020). "First, high level and activity of AhR mediates the invasive/dedifferentiated phenotype of melanoma through the direct regulation of the expression of many genes involved in invasion (COL1A1, COL6A1, COL6A2, CYR61, STC2...) and dedifferentiation phenotypes (CCL2, NTM, NUAK2, SOX9, ABCG2...)." (PMID 36305167, 2022).
colon cancer (1 paper, 2022). "Since the expression levels of CTHRC1, FBN2, NTM, PDGFC, PDLIM3, and SLC16A3 are significantly differentiated among the normal samples, primary tumor, and metastatic tumor, we anticipated that these genes are associated with metastasis in colon cancer." (PMID 35991839, 2022).
heart failure (1 paper, 2021). Inability of the heart to pump blood at an adequate rate to meet tissue metabolic requirements. "Vanins (Vnn) are enzymes that convert pantetheine to vitamin B5, and while absence of Vnn1 activity improved insulin sensitivity in high fat diet-fed animals, its short-term inhibition may have limited value as an anti-diabetic strategy, neurotrimin (Ntm) is a novel biomarker of heart failure." (PMID 34692767, 2021).
idiopathic pulmonary fibrosis (1 paper, 2023). Idiopathic pulmonary fibrosis (IPF) is a nonneoplastic pulmonary disease that is characterized by the formation of scar tissue within the lungs in the absence of any known cause. "NTM1 is upregulated in the lung fibroblasts of patients with idiopathic pulmonary fibrosis compared to the lung fibroblasts of healthy donors, while the level of the neurotrimin protein is reduced in rat bone marrow MSCs during adipogenic differentiation." (PMID 36979822, 2023).
ischemic cardiomyopathy (1 paper, 2025). Ischemic cardiomyopathy is a cardiomyopathy in which a weakness in the muscle of the heart due to inadequate oxygen delivery to the myocardium with coronary artery disease being the most common cause. "Bulk RNA-seq data from the GSE116250 cohort revealed significant overlap between ischemic cardiomyopathy (ICM)-associated differentially expressed genes (DEGs) and FB3-specific markers (THBS4, NTM, NRK, COL14 A1 upregulated; MGST1 downregulated)." (PMID 40447667, 2025).
large cell carcinoma (1 paper, 2021). A malignant epithelial neoplasm composed of large, atypical cells. "In the Oncomine database, there were 6 (3 from LUAD, 2 LUSC and large cell carcinoma) and 1 LUAD cohorts showing downregulation of LSAMP and NTM genes, respectively." (PMID 34202934, 2021).
medulloblastoma (1 paper, 2013). A malignant, invasive embryonal neoplasm arising from the cerebellum. "The miRNA 183/182 cluster, which was downregulated in our series, has also been found to be deregulated in medulloblastoma and prostate cancer, and the cluster has been shown to inhibit cell proliferation and migration by targeting FGF9 and NTM in Schwann cells." (PMID 23776562, 2013).
schizophrenia (1 paper, 2018). A major psychotic disorder characterized by abnormalities in the perception or expression of reality. "Alterations in 11q25 have already been associated with schizophrenia and schizophrenia susceptibility has been associated with SNPs in both OPCML and NTM, making it a considerable risk locus for dysfunctional neural regulation." (PMID 29434535, 2018). "We detected significantly elevated levels of the NEGR1 transcript (1.33-fold increase) and the NTM 1b isoform transcript (1.47-fold increase) in the DLPFC of schizophrenia patients compared to healthy controls." (PMID 29434535, 2018). "Growing evidence suggests that the IgLON family of neural adhesion molecules LSAMP, NTM, NEGR1, and OPCML are important candidates in forming the susceptibility to schizophrenia (SCZ)." (PMID 29434535, 2018).
tumor (4 papers, 2020 to 2022). "Consistently, the protein expression of LSAMP and NTM of the CPTAC cohort revealed that tumor parts expressed lower levels of LSAMP and NTM protein in LUAD; furthermore, the levels of LSAMP and NTM protein were correlated negatively with tumor stage." (PMID 34202934, 2021).
cancer (3 papers, 2014 to 2024). A tumor composed of atypical neoplastic, often pleomorphic cells that invade other tissues. "MicroRNAs were detected in neurotrimin-mediated functions in cancer biogenesis and in Schwann cell responses to peripheral nerve injury." (PMID 39057097, 2024). "The highest hit rate was six, and this for an intronic UCE that is the one and only UCE in the gene neurotrimin (NTM), which has not been associated with cancer." (PMID 25340765, 2014).
infection (1 paper, 2023). The state of being infected such as from the introduction of a foreign agent such as serum, vaccine, antigenic substance or organism. "Most interestingly, hepadnavirus integrates into the host genome within the gene NTM (neurotrimin) 1 h after infection." (PMID 37108169, 2023).
psychiatric diseases (1 paper, 2024). "In contrast, NTM (IgLON2) KO mice only showed minor emotional-related learning deficiencies in the active avoidance test, and in human genetic studies, NTM has not been identified as a risk for psychiatric diseases." (PMID 38370417, 2024).
NTM also shares sentences with these, for which no sentence is quoted: autism (1 paper); bladder cancer (1); cervical cancer (1); colorectal cancer (1); diabetes (1); endometriosis (1); Ewing sarcoma (1); gastric cancer (1); immune disease (1); leiomyoma (1); lung adenocarcinoma (1); mastitis (1); metastatic tumor (1); opioid use disorder (1); oral cancer (1); pancreatic cancer (1); prostate carcinoma (1); rectal cancer (1); salivary gland adenoid cystic carcinoma (1).